INS (insulin)
Diseases named in the same sentence as INS in open-access papers (continued):
Sharing a sentence is not in itself a finding about the gene and the disease.
Insulin resistance (continued). "However, to our knowledge, these studies have all assessed the clinical outpoint of GDM rather than the mechanistically relevant biochemical markers of insulin resistance and insulin secretion." (PMID 35031057, 2022). "Hypomagnesemia may contribute to insulin resistance, as Mg2+ supplementation enhances insulin sensitivity and glucose profiles both in people with and without diabetes." (PMID 36093068, 2022). "Obesity may be one of the most important predictors of DM2 as excess body fat and unfavourable body fat distribution lead to a state of chronic inflammation and insulin resistance, as well as impaired insulin secretion." (PMID 36554003, 2022). "Insulin resistance in the group of women with PCOS caused a further SOD1 activity decrease, while Cu concentration and the value of Cu/Zn was increased when compared to women with normal insulin levels." (PMID 35566673, 2022). "Apart from this, the parameters body weight, BMI, fasting glucose, and insulin resistance exhibited significant decreases in both groups, but in the intervention group, waist circumference, waist/hip ratio, and fasting insulin has also revealed a considerable decline." (PMID 36235638, 2022). "Furthermore, 1,25 D supplementation has been shown to reduce insulin resistance (IR) in individuals with prediabetes and IR and improve insulin secretion, insulin sensitivity and HbA1c." (PMID 36232910, 2022). "Moreover, free fatty acids and accumulation of intracellular TG and other lipid intermediates can impair insulin signaling and contribute to cardiac insulin resistance." (PMID 36120460, 2022). "Conversely, the association was positive with plasma and erythroid contents of cadmium, plausibly because of its capacity to disrupt the endocrine system, provoke insulin resistance, and consequently increase the circulating concentrations of insulin and glucose." (PMID 36711380, 2022). "L. rhamnosus supplementation use as a probiotic could contribute to a significant decrease in plasma triglycerides, low density lipoprotein (LDL)-cholesterol, insulin, and homeostatic model assessment for insulin resistance (HOMA-IR)." (PMID 36671395, 2022). "One can envisage higher fasting GLP-1 may increase circulating insulin, which may lead to insulin resistance among obese patients." (PMID 36355134, 2022). "Again, hypomagnesemia may (partially) explain the insulin resistance in Gitelman syndrome, as Mg2+ is essential for the insulin signalling pathway." (PMID 35894287, 2022). "Insulin tolerance test showed OVX to cause mild insulin resistance and treatment with ActRIIB-Fc did not affect this in either SHAM or OVX mice." (PMID 35024891, 2022). "Nonetheless, another issue to consider is whether PREDIM was validated in a sufficiently wide range of insulin sensitivity values, thus comprising values typical of insulin resistance observable in pregnancy, especially when complicated by GDM." (PMID 36258194, 2022). "Potentially, this might be due a longer half-life of C-peptide compared to insulin, and possibly to the presence of markedly elevated insulin levels due to insulin resistance in a patient with obesity." (PMID 36376919, 2022). "Although there is evidence that elevated BCAA levels hamper insulin signaling pathways, it remains still unclear whether elevated BCAA levels are a cause or rather a consequence of insulin resistance." (PMID 35931683, 2022). "Nevertheless, since all correlations lost their significance after accounting for ppBMI, uncorrected fructosamine concentrations may be more associated with markers of overall adiposity (ppBMI, SAT) than with insulin levels and insulin resistance itself." (PMID 36235652, 2022). "Insulin resistance is a condition that occurs when these hormones make insulin less effective." (PMID 35867537, 2022).
Insulin resistance (continued). "Our results suggest that mice lacking B1 kinin receptor were able to increase their insulin secretion, overcoming the induction of insulin resistance caused by a higher weight gain while on CAF, resulting in a lower increment of the glucose levels during GTT." (PMID 35617279, 2022). "Consequently, the plasma triglyceride (TG) concentration is even higher, leading to lipid accumulation in skeletal muscle, impaired insulin action, and whole-body insulin resistance." (PMID 35380611, 2022). "Hepatic insulin resistance may be lower in Black as compared with white women and the gut-liver axis may prove to be one mechanism by which reduced insulin sensitivity is more prevalent in this group." (PMID 35045086, 2022). "The observed insulin resistance and impaired insulin secretion are similar to those in T2DM." (PMID 35207731, 2022). "In contrast, late pregnancy is better characterized as a catabolic state with decreased insulin sensitivity and increased insulin resistance, which in turn results in increases in maternal glucose and free fatty acid concentrations, allowing greater substrate availability for fetal growth." (PMID 35086506, 2022). "HOMA-IR and HOMA-IS were used to reflect insulin resistance and insulin sensitivity, respectively." (PMID 36407549, 2022). "Given previous reports of blunted effects of IN insulin in individuals with obesity presenting with peripheral insulin resistance we hypothesized that participants with obesity could be less responsive to effects of IN insulin than lean women." (PMID 35397638, 2022). "The ability of aspirin to specifically inhibit the protein inhibitor of kappa light polypeptide gene enhancer in B-cells, kinase beta (IKK-β) and further regulate NF-κB signaling pathway results in attenuated insulin resistance while promoting insulin sensitivity." (PMID 35213966, 2022). "Development of insulin resistance during Mtb infection in mice is age dependent: We analyzed the effects of different diets on the basal glucose and insulin levels 4 weeks post infection (wpi) in mice (juvenile and adult mice infected at 6 and 10 weeks of age, respectively)." (PMID 35329973, 2022). "In addition, both MIIRT and HIIRT also had positive effects on insulin resistance, insulin, and LDL levels." (PMID 35757424, 2022). "A large number of studies have confirmed that insulin resistance and insulin signal transduction defects are important factors in T2DM with chronic psychological stress that can inhibit the PI3K/Akt signaling pathway and affect physiological processes such as autophagy and inflammation." (PMID 36407109, 2022). "Insulin resistance refers to the decrease in the efficiency of insulin to promote glucose uptake and utilization for various reasons, and the compensatory secretion of excessive insulin produces hyperinsulinemia to maintain the stability of serum glucose levels." (PMID 36518760, 2022). "Consumption of foods and meals that induce a lower glycemic response and delay gastric emptying, thus leading to decreased insulin requirements and postprandial glucose excursions, has been proposed as an important strategy to ameliorate postprandial hyperglycemia and insulin resistance." (PMID 35270698, 2022). "In terms of the control of blood sugar and reduced insulin resistance, an insulin pump (CSII) combined with biguanide, DPP-4 inhibitors, sensitizers, and GLP-1 receptor agonists can further reduce FPG, 2hPG, and HOMA-IR levels compared with an insulin pump alone." (PMID 36015100, 2022). "Disordered insulin secretion contributes to the development of insulin resistance and may be an initiating factor in the progression to T2DM." (PMID 36482911, 2022). "With the change in maternal hormone levels in the first trimester of pregnancy, slight insulin resistance and increased insulin secretion may affect fetal growth and energy reserves." (PMID 36675721, 2022).
Insulin resistance (continued). "In this regard, aged HFD female rats showed improved glucose tolerance, suggesting a healthier serum profile of insulin sensitivity, which could be related with the increase in the AT insulin resistance index as well as in the Adpn/Lep ratio." (PMID 36615734, 2022). "According to this hypothesis, defects in hepatic insulin clearance promote chronic hyperinsulinaemia, which in turn leads to insulin receptor desensitisation, target tissue insulin resistance and subsequent glucose intolerance." (PMID 34661756, 2022). "Although the MOD population has higher BMI and insulin resistance, the islet function of the MOD population was the best among the five clusters; thus, the insulin secreted through the excellent islet function can meet the insulin demand in the body under insulin resistance." (PMID 36457559, 2022). "Insulin resistance was assessed by laboratory analysis of fasting blood glucose and insulin levels." (PMID 35576937, 2022). "For instance, saccharin, an artificial sweetener, could potentiate glucose-stimulated insulin release from isolated pancreatic β-cells, leading to insulin resistance and possibly weight gain." (PMID 36017229, 2022). "The basal hyper-tyrosine phosphorylation of IRβ and the non-stimulation of pY- IRβ after insulin injection into the muscle of OZRs established the disruption of insulin signaling, causing insulin resistance." (PMID 36547071, 2022). "Moreover, obesity has been considered as a state of low-grade inflammation due to an excess of cytokines and adipokines, which modify glucose and insulin metabolism and a combination thereof, thus leading to insulin resistance and metabolic syndrome." (PMID 35682832, 2022). "However, HOMA-IR does provide a measure of insulin resistance, establishing that calorie restriction improves insulin sensitivity across all ages of mice." (PMID 36315375, 2022). "Additionally, attenuating adiponectin mRNA synthesis and secretion, and inhibition of insulin signaling in hepatocytes contribute to insulin resistance." (PMID 36248900, 2022). "In youth with CAH, a higher prevalence of insulin resistance has been found compared to their unaffected peers, with significantly higher insulin concentrations and homeostasis model assessment for insulin resistance index (HOMA-IR), even after adjusting for BMI." (PMID 35399922, 2022). "Additionally, probiotic treatment also caused a statistically significant reduction in insulin levels and insulin resistance and a statistically significant rise in insulin sensitivity." (PMID 36084951, 2022). "Additionally peripheral insulin resistance can occur in select tissues (i.e., hepatic insulin resistance which is defined as the failure of insulin to suppress hepatic glucose production)." (PMID 35884888, 2022). "In this critical appraisal, we discuss the role of sugar intake and insulin on dopamine metabolism in patients with PD and how this could influence the potential neurodegeneration mediated by insulin resistance." (PMID 35956417, 2022). "Additionally, increased fasting blood glucose and insulin resistance were also observed in Gpx4−/− AT mice, and spontaneously produced impaired insulin signaling in the liver, resulting in systemic inflammation and disorders of glucose metabolism." (PMID 36479119, 2022). "Reduced IRS-1 and GLUT4 expressions will contribute towards lower insulin-induced glucose transport, and these could explain the link between vitamin D deficiency, high serum PTH levels, and insulin resistance." (PMID 35859985, 2022). "On the other hand, type 1 DM (T1DM) is not only the consequence of severe beta-cell deficiency, but is also burdened, over time, by some degree of insulin resistance due to insulin overtreatment-related receptor downregulation, advanced glycation endproducts (AGE) accumulation, and more." (PMID 35646861, 2022).
Insulin resistance (continued). "We speculate that, in addition to an OGTT, fasting insulin could be assessed to estimate beta cell function and insulin resistance in pregnant women so as to enable personalized and effective care." (PMID 35745174, 2022). "Given that skeletal muscle is responsible for 75% of insulin-mediated glucose disposal, the presence of chronic insulin resistance will severely impact muscle mass, and thus reducing creatine excretion and increasing the probability of major adverse cardiac events." (PMID 35665251, 2022). "Increased insulin levels and insulin resistance also contribute to the pathogenesis of PCOS." (PMID 35924049, 2022). "Significantly improved glucose metabolism, including FPG fasting insulin, and insulin resistance." (PMID 35910625, 2022). "Moreover, patients with a higher FA Score presented lower insulin sensitivity and higher hepatic insulin resistance (p < 0.05)." (PMID 34609622, 2022). "Ceramides decrease the plasma content during pioglitazone treatment, and inhibition of ceramide synthesis or stimulation of ceramide degradation improves insulin signaling, indicating indispensable participation of ceramides in the development of obesity and insulin resistance." (PMID 36230963, 2022). "Thus, the defective insulin signaling appears to be at the crux of insulin resistance and PD pathogenesis." (PMID 35761385, 2022). "Finally, in our study, insulin resistance is related to age, i.e., older children have more IR, which is consistent with the insulin peak that is described in adolescence." (PMID 36296916, 2022). "Oral administration of RSV in humans improves insulin secretion and insulin resistance by protecting pancreatic β cells from oxidative stress, suppresses glucagon production after meals by improving insulin metabolism, and reduces fasting blood sugar and A1C hemoglobin." (PMID 35409389, 2022). "Studies have confirmed that insulin antagonism is more evident in central obesity, and WC is recognized as an important indicator for measuring central obesity, which can better reflect insulin resistance." (PMID 34979974, 2022). "The development of insulin resistance in the SERCA2aThr484Ala knockin cardiomyocytes suggests that SERCA2a is not only a target of the insulin−PKB pathway but also a critical regulator of myocardial insulin signaling." (PMID 39872684, 2022). "If the insulin resistance of the participants was in fact increased, this might have exacerbated the decrease in insulin secretion and the increase in FPG." (PMID 35947600, 2022). "Interestingly, a decreased insulin response or insulin resistance is often observed in adolescents with whom growth and sex hormones play a decisive role." (PMID 36364951, 2022). "Furthermore, PTH is associated with insulin resistance, and one study showed that PTH decreased insulin-stimulated glucose absorption in rat adipocytes." (PMID 35209709, 2022). "Insulin resistance and hyperinsulinemia increase the levels of intracellular and extracellular Aβ, resulting in Aβ accumulation and abnormal tau phosphorylation via the insulin-signaling activation of the GSK-3b cascade." (PMID 35682821, 2022). "Furthermore, drugs that can act as insulin sensitizers and/or bypass insulin resistance in the brain offer a unique opportunity to address cognitive deficits and improve lives of the patients with schizophrenia." (PMID 34108878, 2021). "Therefore, a larger RcGV is thought to reduce peripheral insulin resistance and have a regulatory effect on insulin release." (PMID 33855197, 2021). "Altered gene expression in specific organs may be reflected in whole blood; hence, our results may reflect obesity and/or insulin resistance-related organ dysfunction in the insulin-resistant individuals." (PMID 34886800, 2021). "Besides, HFD diet group presented a remarkable increase in plasma insulin concentration and HOMA-IR index, which is closely linked to hepatic insulin resistance in NAFLD." (PMID 34943104, 2021).
Insulin resistance (continued). "The PDBs in the forms of cytokines and signaling molecules could enhance the differentiation potential of stem cells into insulin-secreting cells, which may inhibit insulin resistance." (PMID 34805412, 2021). "However, some changes in the metabolism of insulin (hyperinsulinemia and insulin resistance) and lipids levels in serum (hypertriglyceridemia) were demonstrated in pre-term fetuses." (PMID 33499108, 2021). "This may result from weakened insulin signaling, as FOXO-mediated transcription is negatively regulated by insulin and transient insulin resistance has been reported to occur for at least 48 hours in skeletal muscle following a bout of ECs." (PMID 33710344, 2021). "A vicious circle has been proposed: SARS‐CoV‐2 decreases insulin secretion and promotes the appearance/worsening of insulin resistance, inducing hyperglycaemia, which, in turn, may further damage β‐cells, with a worsening of insulin resistance." (PMID 34277995, 2021). "We hypothesized that in patients with previously identified DM, glucose-insulin homeostasis, drug interaction, and insulin resistance may also affect the result." (PMID 33800924, 2021). "Body mass index (BMI), fasting glucose and insulin, 1 h glucose, 2 h glucose and insulin, hemoglobin A1 (HbA1C), homeostasis model of assessment-insulin resistance (HOMA-IR), and triacylglycerides (TG) were significantly higher in the GDM group than in the control group (p < 0.05)." (PMID 34212051, 2021). "However, many obese patients develop insulin resistance, owing to the inability of insulin to regulate the metabolism of peripheral tissues." (PMID 33868169, 2021). "In addition, altered insulin secretion, dyslipidemia, fat deposition in the liver and adipose tissues, and insulin resistance become aggravating factors for MetS." (PMID 33800403, 2021). "In addition to the classic peripheral insulin-sensitive tissues, such as muscle, liver, and adipose tissue, insulin resistance has been shown to occur in the brain, even in the absence of concurrent type 2 diabetes." (PMID 33810179, 2021). "Insulin resistance is a pathology inherent to the metabolic syndrome and, as over one-third of Americans have metabolic syndrome and 88% exhibit at least one of its markers, optimizing insulin sensitivity should be a dietary priority." (PMID 33921683, 2021). "Current invasive methodologies for measuring insulin resistance reliably assess hepatic and peripheral tissue responsiveness to insulin, but the extensive time and resources required to perform these metabolic assessments relegate these techniques to the research arena." (PMID 34084151, 2021). "Similarly, as a crucial proinflammatory mediator, tumour necrosis factor (TNF) induces insulin resistance by impairing insulin signalling through serine phosphorylation." (PMID 34675276, 2021). "Given the insulin-mediated induction and the progressive increase of serum FGF21 level with extent of impaired glucose-tolerance, these findings imply that insulin resistance is substantially associated with the elevated serum FGF21 concentration or the presence of FGF21 resistance." (PMID 33668309, 2021). "This could be due to the relative increment of peripheral insulin resistance in the afternoon and lower insulin level after glucose administration in the afternoon than in the morning." (PMID 34337059, 2021). "Resistin counters insulin action and is proposed to link insulin resistance and obesity." (PMID 34299261, 2021). "Therefore, LECT2 can be an important marker to explain how the fatty liver leads to insulin resistance in obesity since its deletion of LECT2 increases insulin sensitivity in skeletal muscle in rats." (PMID 33807959, 2021). "However, there were no significant changes in the plasma levels of fasting glucose, glycated hemoglobin, insulin, homeostatic model assessment for insulin resistance, HDL-C, LDL-C, and remnant COH with SLO treatment relative to placebo treatment." (PMID 34146594, 2021).